LHX6 (LIM homeobox 6)
Description:
Probable transcription factor required for the expression of a subset of genes involved in interneurons migration and development. Functions in the specification of cortical interneuron subtypes and in the migration of GABAergic interneuron precursors from the subpallium to the cerebral cortex (By similarity).
Synonyms: LHX6.1; hLHX6
Tractability: No criterion of Open Targets' tractability assessment is met for any kind of drug.
Gene: Protein-coding gene on chromosome 9 (122,202,577 to 122,229,626, reverse strand). Ensembl gene ENSG00000106852.
Subcellular location: Nucleus
Subcellular location (Human Protein Atlas): Nucleoplasm; Cytosol
Gene Ontology:
Molecular function: protein binding; sequence-specific double-stranded DNA binding; DNA-binding transcription factor activity; DNA-binding transcription factor activity, RNA polymerase II-specific; RNA polymerase II transcription regulatory region sequence-specific DNA binding; DNA binding; sequence-specific DNA binding
Biological process: cell maturation; cerebral cortex GABAergic interneuron migration; cerebral cortex radially oriented cell migration; cerebral cortex tangential migration; forebrain neuron development; neuron differentiation; regulation of transcription by RNA polymerase II; regulation of DNA-templated transcription
Cellular component: nucleus; chromatin
Genetic constraint (gnomAD): Loss-of-function variants: 13 observed, 34.84 expected, observed/expected ratio (o/e) 0.37, 90% interval 0.24 to 0.59. The upper end of that interval is the gene's LOEUF score, 0.59, which puts it in group 2 of 6, group 1 being the genes least tolerant of losing a copy. Missense variants: 347 observed, 421.26 expected, observed/expected ratio (o/e) 0.82, 90% interval 0.75 to 0.9. Synonymous variants: 227 observed, 187.86 expected, observed/expected ratio (o/e) 1.21, 90% interval 1.08 to 1.35.
Homologues: Orthologues: macaque LHX6 (99% identical), chimpanzee LHX6 (99% identical), pig LHX6 (98% identical), rat Lhx6 (98% identical), mouse Lhx6 (98% identical), dog LHX6 (93% identical), guinea pig LHX6 (92% identical), tropical clawed frog lhx6 (82% identical), zebrafish lhx6a (72% identical), zebrafish lhx6b (37% identical). Paralogues in human: LHX8 (51% identical), ZFHX3 (31% identical), ZFHX4 (29% identical), LHX9 (28% identical), LHX2 (27% identical), LMX1B (26% identical), LHX1 (26% identical), ZFHX2 (26% identical), LMX1A (25% identical), LHX5 (25% identical), LHX3 (23% identical), LHX4 (22% identical), and 8 more.